AR (androgen receptor)
Diseases named in the same sentence as AR in open-access papers (continued):
Sharing a sentence is not in itself a finding about the gene and the disease.
prostate tumors (continued). "Prostate tumor and normal prostate tissues show elevated AR expression instead of ESR1 expression." (PMID 35594510, 2022). "The remarkable reliance of PCa on AR signalling led to the generation of effective targeted therapies, such as enzalutamide, abiraterone acetate and other small molecule inhibitors of the AR pathway, which have significantly improved the clinical management of non‐resectable prostate tumours." (PMID 35014179, 2022). "Increased abundance of monounsaturated lipids and of elongated fatty-acid chains in phosphatidylinositol and phosphatidylserine lipids are noticed in prostate tumors, and importantly, phospholipid composition is altered in patients with response to AR inhibition." (PMID 35682963, 2022). "In summary, the heterogeneity of prostate tumours is a natural challenge to AR target therapy." (PMID 35832549, 2022). "Pioneer transcription factors, including FOXA1, HOXB13, and GATA2, as well as the transcription factor ERG, have prominent roles to play in earlier, hormone-sensitive stages of the disease and in CRPC where AR signaling remains a mainstay of prostate tumor growth." (PMID 36212399, 2022). "And studies have found that in mice bearing TC1 murine prostate tumors, whether they were treated with antiandrogen therapy or silencing of AR, the expression of IL-6 and STAT3 in mouse tumors would increase." (PMID 33995485, 2021). "Furthermore, they control the androgen receptor activity in prostate tumors and the estrogen receptor action in the mammary tumors." (PMID 34573087, 2021). "Although these therapies are effective in controlling prostate tumors dependent on or addicted to AR signaling, prostate tumors surviving the onslaught of potent treatments may evolve and develop drug resistance." (PMID 34884545, 2021). "qRT-PCR analysis was conducted on the cells bound to the microchannels to detect mRNAs associated with prostatic tissues, androgen receptor (AR), and prostate-specific antigen (kallikrein-related peptidase 3 or KLK3), as well as prostate tumor-derived genes prostate cancer antigen 3 (PCA3) and PSMA." (PMID 34771706, 2021). "However, patients frequently develop castration resistance, making prostate tumor cells resistant to androgen deprivation therapy despite the retention or amplification of the androgen receptor in prostate tumor cells." (PMID 34829800, 2021). "Taken together, we speculate that GHSROS primes prostate tumors for androgen receptor-independent growth." (PMID 33585078, 2021). "While suppression of AR activity by androgen receptor pathway inhibitors (ARPIs) is initially effective in almost all men, prostate tumours inevitably develop resistance and progress to a lethal disease state known as castration-resistant prostate cancer (CRPC)." (PMID 34382934, 2021). "Androgen receptor (AR)-null prostate tumors have been observed in 11–24% of patients." (PMID 33572730, 2021). "Androgen receptor (AR) is a nuclear hormone receptor that is activated in response to the binding of androgens, and its abnormality has been proven to be primarily responsible for the development, growth and progression of prostate tumors." (PMID 34948018, 2021). "It has been identified that androgens can regulate VEGF levels through HIF activation in prostate tumors, and inhibition of androgen receptor and HIF may provide a new therapeutic option." (PMID 35211477, 2021). "MiR-212 is downregulated in prostate tumor cells, and it suppresses the transcription of AR and AR-V7 through direct targeting hnRNPH1, which may regulate AR mRNA transcription or splicing." (PMID 33869227, 2021).
prostate tumors (continued). "Results from this study demonstrate that in addition to the inhibition of androgen receptor (AR), the key modulator of prostate tumor growth, arctigenin was able to increase the expression of Nkx3.1 and suppress tumor angiogenesis to inhibit prostate tumor growth in obese conditions." (PMID 31996731, 2020). "Interestingly, among the common up-regulated targets, UGT2B15 and HOTAIR were described to be inhibited by AR in prostate tumors and activated by ESR1." (PMID 32041153, 2020). "Intriguingly, application of our metagene approach to GEMMs and human cell lines provided also insights into novel strategies that could revert prostate tumors to a more luminal state and perhaps enhance or restore sensitivity to AR-based therapies." (PMID 31936761, 2020). "For example, EZH2-S21phospho may reduce EZH2 binding to histone H3 and enhance its interactions to non-PRC2 partners, such as androgen receptor (AR) in advanced prostate tumor and STAT3 in GBM." (PMID 33327550, 2020). "AR signaling, however, is hijacked in prostate tumors, driving disease progression." (PMID 32820253, 2020). "In prostate tumors, with loss of PTEN, there are decreased levels of AR signaling." (PMID 33062889, 2020). "In addition, decorin is known to suppress prostate tumor growth through inhibition of epidermal growth factor and androgen receptor pathways." (PMID 32155897, 2020). "Importantly, our results demonstrate that LRIG1 represents an androgen receptor (AR) regulated gene and exhibits tumor-suppressive functions in both xenograft and genetic prostate tumor models." (PMID 31792211, 2019). "This highlights the need for further investigation to determine whether MCL‐1 is a critical target in AR‐v7 expressing prostate tumors." (PMID 31228231, 2019). "Interestingly, AR can form complexes with β-catenin, a key effector protein of the Wnt/β-catenin signaling pathway, and in prostate tumors β-catenin regulates activation of downstream AR pathways." (PMID 31139042, 2019). "Thus, ETS− and ETS+ prostate tumors both show comparable expression of AR, yet demonstrate unique AR-dependent alterations in biological pathways that drive tumorigenesis." (PMID 30367117, 2019). "In search for the molecular basis by which transgenic AR expression and p16INK4a deletion regulate prostate tumorigenesis, we performed RNA-sequencing analysis to examine the global transcriptome profiles in the mouse prostate tumor samples." (PMID 30677079, 2019). "A better understanding of how prostate tumors develop might lead to new treatments in which the androgen receptor is blocked in combination with other new protein targets." (PMID 29334357, 2018). "The vast majority of prostate tumors depend on the AR pathway for survival." (PMID 30135717, 2018). "Nevertheless, every treatment-failed prostate tumor harbors both AR−/lo and AR+/hi cells." (PMID 30190514, 2018). "Our study links AR expression heterogeneity to distinct castration/enzalutamide responses and has important implications in understanding the cellular basis of prostate tumor responses to AR-targeting therapies and in facilitating development of novel therapeutics to target AR−/lo PCa cells/clones." (PMID 30190514, 2018). "Thus, while AR-negative PCa accounts for a minority of prostate tumors, they are becoming more common and will require a different therapeutic strategy than classic AR-positive PCa." (PMID 30135717, 2018). "Similarly, we have recently shown that SLC35F2 is a direct transcriptional target of AR, and that its expression in human prostate tumors is correlated with AR activity and tumor androgen levels." (PMID 28350329, 2017).
prostate tumors (continued). "In addition, intracrine androgen synthesis can occur in prostate tumours and aberrant activation of alternative signaling pathways can also activate the AR." (PMID 27903893, 2017). "The coordinated action of miR-21 and androgen receptor signaling, suppresses TGFBR2 levels through binding to its 3'UTR, enhancing androgen receptor signaling, thereby exerting its oncogenic effects on prostate tumors, through inhibition the suppressor activity of the tumor by TGFβ pathway." (PMID 28320379, 2017). "We found a shift in the significance of the receptors for tumor recurrence; higher rates of AR expression are unfavorable for prostate tumor in younger patients, however it loses its significance in the oldest group, in contrast to ESR1, where higher expression is generally unfavorable." (PMID 29206234, 2017). "However, we recognize the physiological limitations of developing a ligand-dependent AR-interactome network based upon the proteomic findings of a single human prostate tumor cell line, such as LNCaP." (PMID 27365400, 2016). "However, ELK1 is expressed in the clinical spectrum of prostate tumors, and in PCa cells the activation of AR target growth genes through ELK1 was constitutive and did not entail hyper-phosphorylation or activation of immediate early genes." (PMID 27793987, 2016). "Because of the heterogeneity of human prostate tumors, Ad-522E-TK may be applied as an adjunct therapy with other AR-targeting modalities for treatment of hormone refractory and bone metastatic prostate cancers." (PMID 27054343, 2016). "More specifically, streptavidin chromatography was used to affinity-purify streptavidin-binding peptide-tagged wild-type AR (SBP-AR) from the cytosolic compartment in the unliganded (i.e. androgen-depleted) and liganded (i.e. androgen-stimulated) states in LNCaP prostate tumor cells." (PMID 27365400, 2016). "Based upon these findings, we speculate that many of the ligand-sensitive proteins identified in the proteomic screen are physically linked, directly or indirectly, to molecules involved in ligand-mediated AR activation/function in prostate tumor cells." (PMID 27365400, 2016). "Next, we wanted to test whether disruption of the Golgi apparatus had any effect on AR-mediated transcription in prostate tumor cells." (PMID 27365400, 2016). "Next, we wanted to test whether SBP-AR underwent ligand-dependent cytoplasmic-nuclear translocation similar to that in AR-T877A in androgen-sensitive LNCaP prostate tumor cells." (PMID 27365400, 2016). "The androgen receptor (AR) plays a central role in prostate tumor growth." (PMID 27248322, 2016). "Most early stage and advanced prostate tumors depend on AR for growth (6, –, 11)." (PMID 27793987, 2016). "Thus, by sustaining ER homeostasis, fatty acid metabolism plays a crucial role- particularly in PTEN null prostate tumors- in maintaining energetic homeostasis and AR levels." (PMID 27248322, 2016). "In addition, the M895V substitution was detected once, underlining the importance of having a compound such as BAY 1024767 for blockade of this AR mutant which was originally identified in a primary prostate tumor." (PMID 26760770, 2016). "Moreover, in human prostate tumor tissue, cells with low AR expression exhibit high STAT3 activity and coexpress CSC markers, including Nanog and CD44." (PMID 26880966, 2016). "Importantly, enriched networks in the AS sample were concordant with known biochemical processes that modulate AR function(s) at the molecular level in prostate tumor cells." (PMID 27365400, 2016). "Notably, PSMA7, a subunit of the catalytic 20S core proteasome that potentiates AR-mediated transcription when overexpressed in prostate tumor cells, was enriched in the AS sample." (PMID 27365400, 2016). "There was greater enrichment for the top-ranked pathways in the AD sample, which suggests that these protein networks may be active under conditions of androgen depletion to modulate AR function in prostate tumor cells." (PMID 27365400, 2016).
prostate tumors (continued). "Thus, these molecules are predicted to modulate AR transcriptional activity in prostate tumor cells." (PMID 27365400, 2016). "Interestingly, RNF6 is also an AR corepressor, which demonstrated that it is a promoter-dependent coregulator of AR transcription in prostate tumor cells." (PMID 27365400, 2016). "This shortcoming has an even greater significance in the context of predicting how this molecular machinery might become perturbed and contribute to aberrant AR activation in prostate tumor cells." (PMID 27365400, 2016). "Because of the heterogeneity of both primary and metastatic prostate tumors, hON-522E-mediated gene therapy may be applied as an adjuvant to AR-targeted therapeutics for treating metastatic CRPC." (PMID 27054343, 2016). "In this model, we predict that i) HES5 expression in benign epithelial cells contributes to HES6 repression and ii) HES5 promoter methylation and silencing in prostate tumours potentiates AR activation of HES6 to start an oncogenic feed-forward transcriptional signalling network." (PMID 25560400, 2015). "While this effect was concluded to result from the alleviation of AR-mediated repression of Zeb1 expression, androgen depletion-induced EMT could also be driven by HIF-1α, as androgen deprivation caused hypoxia in prostate tumors." (PMID 25821081, 2015). "Thus AR promotes the migration and invasion of prostate tumor cells through Matrigel via either of two laminin-specific integrins." (PMID 25730905, 2015). "Besides NF-κB dependent interleukin 6 pathway not only support prostate tumor survival and prevent apoptotic event but also activate AR during emergence of androgen independent PCa." (PMID 26295410, 2015). "Therefore, it is possible that during the development of ADT-driven SCNC, ADT induces an up-regulated expression of miR-204, which, in turn, reduces AR expression, and eventually enables certain prostate tumor clones to assume a more NE phenotype." (PMID 25797256, 2015). "Finally, the AR transgene and mutated derivatives may be used to study testosterone regulation of physiologically important processes in other tissues including oocyte development, sexual differentiation, heart function, muscle mass maintenance and prostate tumor progression." (PMID 25803277, 2015). "In these diseases, NRs have proven to be effective therapeutic targets with numerous drugs targeting many NRs including estrogen receptor (ER) in breast, ovarian, and endometrial cancers, androgen receptor (AR) in prostate tumors, and glucocorticoid receptor (GR) in some hematological malignancies." (PMID 26217306, 2015). "It is important to document the expression profile of AR-FL and AR splice variants under treatments of PI3K/AKT inhibitors, since sustained AR expression and function are one of the critical molecular mechanisms by which prostate tumors progress into CRPC." (PMID 25360799, 2014). "We investigated whether enzalutamide-mediated immunogenic modulation could improve the sensitivity of prostate tumor cells engineered to overexpress AR to T cell-mediated killing." (PMID 25344864, 2014). "This study aims to investigate whether PI3K/AKT inhibitors have any off-target effects to AR gene expression in a panel of PCa cell lines that represent prostate tumor cells with a broad range of genetic variations." (PMID 25360799, 2014). "In this study, we firstly describe that the AR is one of the targets of shikonin in vitro, inhibition of which leads to cell death in human prostate tumor cells, shikonin is highly effective in reducing the protein level of AR and the transcriptional activity of AR." (PMID 24573652, 2014). "We previously established a TRAMP mouse prostate tumour model with deletion of AR in prostate epithelial cells (pesARKO/TRAMP) and found this genetic ablation of AR unexpectedly increased metastasis of TRAMP prostate tumours, supporting a suppressive role for AR in PCa metastatic progression." (PMID 23982944, 2013).
prostate tumors (continued). "Finally, AR has recently been suggested to function as a tumor suppressor in epithelium to suppress prostate tumor invasion and metastasis." (PMID 23359804, 2013). "Indeed, the emerging understanding of the mechanism of therapeutic failure of advanced prostate tumors involves upregulation of AR or activation of its transcriptional activity via a ligand-independent manner leading to castration-independent disease." (PMID 22641253, 2012). "In addition to CRPC, AR is expressed in nearly all prostate tumors and is required for tumor maintenance." (PMID 22509301, 2012). "The androgen receptor (AR) is expressed in a subset of prostate stromal cells and functional stromal cell AR is required for normal prostate developmental and influences the growth of prostate tumors." (PMID 21267466, 2011). "Furthermore, sensitisation of the androgenic response by multi-functional growth factor signalling pathways is thought to be one of the mechanisms through which AR contributes to the emergence of androgen-independent prostate tumours." (PMID 19888222, 2009). "These exceptions, however, may have important implications for ligand-independent signaling of the AR as part of the ablation-resistant phenotype in advanced prostate tumors." (PMID 18997859, 2008). "Therapies targeting the input of the AR into the Wnt signaling pathway may lead to effective treatments for castration-refractory prostate tumors." (PMID 18218096, 2008). "The AR plays a role in the growth of both healthy prostate and prostate tumors." (PMID 19025659, 2008). "We suggest that AR and ERα-associated PI3K could represent novel target proteins for the antitumoral activity of RES in human prostate tumours, establishing a common mechanism with other hormone-dependent cancers such as breast." (PMID 17486135, 2007). "In this work, we have used LNCaP (AR positive, ERα negative) and PC-3 (AR negative, ERα positive) prostate tumour cells to address the mechanism through which RES modulates the AR- and ERα-associated PI3K activity." (PMID 17486135, 2007). "Based on their differential expression, we reasoned that CK5, PSA, and AR could serve as predictive biomarkers for identification of subtypes of prostate tumors that would benefit from dasatinib treatment." (PMID 18047674, 2007). "Here, using androgen receptor (AR)-positive LNCaP and oestrogen receptor alpha (ERα)-expressing PC-3 prostate tumour cells, we have analysed whether the antiproliferative activity of RES takes place by inhibition of the AR- or ERα-dependent PI3K pathway." (PMID 17486135, 2007). "This different potency of RES in prostate tumour cells could be related to downregulation of the expression and function of the AR in androgen-responsive LNCaP cells." (PMID 17486135, 2007). "Thus, regardless of mutation origin, perturbation of the FOXA1/AR-mediated regulatory program emerges as a unifying mechanism that drives prostate tumor formation and progression." (PMID 41468516, 2025). "Therefore, more investigations with new and biologically relevant in vivo models and systems should be warranted to determine the biological role of stromal AR as prostate tumor niches during the course of PCa development, progression, and hormone refractoriness." (PMID 39369165, 2024). "Interestingly, AR mutations and amplification events are nearly exclusively found in metastatic prostate tumor samples, but not in primary tumor samples." (PMID 36937425, 2023). "Some studies have found that NRF2 and AR can regulate each other in the prostate, and it is speculated that they, along with AR, may play a critical regulatory role in the formation, development, and treatment of prostate tumors." (PMID 35770119, 2022).